EGFR (epidermal growth factor receptor)
Diseases named in the same sentence as EGFR in open-access papers (continued):
Sharing a sentence is not in itself a finding about the gene and the disease.
cancer (continued). "Over 120 small-molecule kinase inhibitors (SMKIs) have been approved worldwide for treating various diseases, with nearly 70 FDA approvals specifically for cancer treatment, focusing on targets like the epidermal growth factor receptor (EGFR) family." (PMID 38791529, 2024). "Cannabinoids are also involved in reducing cancer cell growth by modulating the EGFR-RAS-RAF-MAPK pathway." (PMID 38396679, 2024). "These marker genes represent multiple malignant phenotypes of cancer, including tumorigenesis (EGFR, MYC), cell invasion (ITGB1 and VIM), and angiogenesis (VEGFA), among others." (PMID 38191424, 2024). "Cetuximab, a drug targeting EGFR (a protein that supports cancer cell growth), is often used but has limitations in effectiveness." (PMID 39594688, 2024). "The EGFR-directed micellar particles were small enough to efficiently move into the cancer tissues via the EPR (enhanced permeability and retention) effect, showing higher targetability and therapeutic efficiency when compared to the untargeted one." (PMID 38892434, 2024). "Expectedly, the PA-MSHA and Gefitinib combination resulted in increased caspase-3/caspase-9 cleavage and inhibition of EGFR-dependent activation of the AKT/ERK pathway involved in cancer cell survival." (PMID 38339275, 2024). "A comprehensive cardiovascular assessment is therefore crucial before initiating cardiotoxic EGFR-TKIs, ideally at cancer diagnosis and before starting treatment." (PMID 39211774, 2024). "This work demonstrates that increased NEU-1 expression is essential in EGFR signaling, which promotes cancer progression and metastasis." (PMID 39194692, 2024). "Aberrant EGFR activation has been observed in multiple cancers including gliomas, commonly driven by hyperactivating mutations and gene amplification." (PMID 38615034, 2024). "The journey is far from over, but the strides made in understanding EGFR-driven cancers and developing targeted therapies provide hope for improved patient outcomes and a future where precision medicine becomes the standard of care in oncology." (PMID 38611728, 2024). "At the same time, CXCL1 expression in cancer cells is dependent on epidermal growth factor receptor (EGFR) ligands derived in endothelial cells." (PMID 38673949, 2024). "As part of in vivo cancer therapy, the anti-EGFR-MPB nanocomposite was injected to the BALB/c nude mouse through the tail vein area." (PMID 39525484, 2024). "Combining MET inhibitors with EGFR inhibitors like gefitinib or erlotinib has shown enhanced efficacy in overcoming resistance in certain cancers." (PMID 39769452, 2024). "Currently, EGFR tyrosine kinase activity is recognized as a promising therapeutic target for cancer treatment." (PMID 39291996, 2024). "Recently, researchers have continued to explain crosstalk between Notch and EGFR to dissect the mechanisms for a better understanding of how cancer cells apply the Notch pathway to counteract the inhibitory effects of EGFR targeting." (PMID 39092224, 2024). "As a proof of concept, we used cetuximab as a model IgG to develop fluorescent VLPs that specifically target cancer cells overexpressing EGFR, resulting in an interesting nanoplatform for cancer theranostics." (PMID 38673914, 2024). "We sought to evaluate if the EGFR inhibitor osimertinib would perform in real-word populations in a manner expected by the registration trial of this anti-cancer agent." (PMID 38539415, 2024). "A fluorescent nanoplatform was created to target cancer cells overexpressing EGFR, presenting a promising avenue for cancer theranostics." (PMID 39851281, 2024). "Specifically, positive EGFR staining provided a distinct demarcation between the cancer cells and the stromal components, corroborating the successful incorporation of these cell types into the organoid structure." (PMID 39766891, 2024). "Currently, EGFR has emerged as a prominent target for cancer therapy due to its overexpression or abnormal expression in various human epithelial tumors." (PMID 39766327, 2024).
cancer (continued). "The EGFR is a cell surface receptor that plays a key role in cancer cell proliferation, differentiation, and migration." (PMID 38927911, 2024). "EREG also showed an increase in the cell migration and invasion of cancer cell lines with the abundant expression of EGFR in our study." (PMID 38673992, 2024). "USPs, which play a role in the recycling and degradation pathway of EGFR, have emerged as targets for intervening in EGFR-induced cancer development and progression." (PMID 39695128, 2024). "Functional EGFR was detected in EVs released by several cancer cell lines, such as A431, A549, and DLD-1." (PMID 39697631, 2024). "An inverse correlation between the expression levels of EGFR and E-cadherin was previously demonstrated in various cancers." (PMID 38338029, 2024). "The overexpression of EGFR on cancer cells usually exceeds that of PD-L1, which is why LCE-K demonstrates a lower EC50 value (28.6 nM) and significantly reduced maximum binding." (PMID 38804304, 2024). "Modifying αCD3 and αEGFR on DEX enables dual-specificity binding to T cell surface CD3 and cancer cell surface epidermal growth factor receptor (EGFR), promoting interaction between T cells and cancer cells." (PMID 39347944, 2024). "These cancer cells can circumvent the EGFR-mediated growth signal blockade by developing an alternative growth pathway, such as a K-Ras mutation-driven growth signal." (PMID 39596025, 2024). "Key pathways in cancer metastasis include epidermal growth factor receptor (EGFR), Wnt/β-catenin, and transforming growth factor-β (TGF-β)." (PMID 39850884, 2024). "Preclinical studies of concomitant EGFR/β1 integrin targeting in HNSCC documented the existence of certain cancer models refractory to this approach." (PMID 38378518, 2024). "One such surface receptor that is frequently seen overexpressed on the surface of malignant tumors is EGFR." (PMID 38592437, 2024). "Recently, it was demonstrated that EGFR activation in human cancer cells results in increased glucose uptake and lactate production in a PKM2 expression dependent manner." (PMID 38514913, 2024). "Consistently, RT‐PCR analysis showed that the expression of EGFR was lower in PCs as compared to cancer cells." (PMID 39435643, 2024). "The heightened glycolysis and increased lactate production observed in cancer cells significantly contribute to the development of resistance to EGFR-TKIs." (PMID 38255882, 2024). "EGFR is the most extensively researched receptor tyrosine kinase due to its role in cancer progression and as a prognostic predicator." (PMID 38474312, 2024). "As the EGFR pathway is upstream of numerous cancer cell growth pathways, we employed a commercially available proteome profiler array to unbiasedly uncover notable signaling changes in HGSOC cells following rAREG exposure." (PMID 38831884, 2024). "EGFR is a transmembrane protein, a member of a large family of receptors involved in developmental biology and cancer." (PMID 39051331, 2024). "The cohort comprised 132 patients from two cancer centers in China, with a median follow-up time of 21.7 months from the onset of EGFR-TKI resistance." (PMID 39015563, 2024). "The endocytic degradation of epidermal growth factor receptor (EGFR) can induce cancer cells to detach from the extracellular matrix, ultimately triggering apoptosis, known as anoikis." (PMID 38663918, 2024). "Recent research efforts have been focused on developing new anticancer therapies that specifically target the EGFR signal transduction pathway, as the EGFR tyrosine kinase is involved in the initiation and progression of various cancers." (PMID 38266021, 2024). "A multifaceted interplay between GPER and EGFR has been demonstrated in diverse cancer cell lines, including BC cells." (PMID 38886784, 2024). "Through CRISPR Cas9, the anti-tumor effect can be greatly improved through knockout of cancer-causing genes, such as DNA methyltransferase 1 (DNMT1) gene, survivine gene, and EGFR gene." (PMID 39407665, 2024).
cancer (continued). "By inducing the degradation of multiple client proteins, PU-H71 disrupts critical signaling pathways such as MAPK, PI3K/Akt, JAK/STAT, EGFR, and mTOR, which are essential for cancer cell survival, proliferation, and metastasis." (PMID 39564119, 2024). "The EGFR signaling pathway includes several sufficient targets for the treatment of human cancers including NSCLC." (PMID 38953007, 2024). "In cancer cells, focal amplification of multiple oncogenes, including EGFR, ERBB2, MYC, BRAF, CDK4, and MDM2 is observed." (PMID 39202666, 2024). "It has been found that EGFR is overexpressed in a variety of cancer cells, including those from the head and neck, breast, esophagus, and lung." (PMID 39652601, 2024). "These EVs were able to activate EGFR signaling in stromal cells, indicating their relevant role in the crosstalk between leukemic and stromal cells, which promotes cancer cell proliferation." (PMID 39697631, 2024). "MAPK cascade plays a key role in tumorigenesis wherein genetic alterations in KRAS and EGFR genes are leading trigger factors of cancer." (PMID 38374954, 2024). "In this study, we found that ADCs can specifically deliver aminobisphosphonate to cancer cells that consistently express EGFR." (PMID 38610932, 2024). "Due to the EGFR’s pivotal role in cancer pathology, EGFR inhibitors have become a promising avenue for therapeutic intervention." (PMID 39337496, 2024). "Our findings reveal the relationship between EGFR tyrosine kinase activity and the induction of autophagy-mediated cancer cell death in NSCLC cells treated with combined strategies." (PMID 38764025, 2024). "Targeted therapy is a specialized cancer treatment that uses drugs to target specific mutant proteins, such as EGFR, ALK, and ROS1, which drive the growth of cancer cells." (PMID 38254898, 2024). "Previous studies have demonstrated that inhibiting PDK1 can enhance the anticancer effect of EGFR-TKIs in malignant tumors, including NSCLCs16,17." (PMID 38689087, 2024). "VV enters cells via receptor-mediated endocytosis, and its replication depends on EGFR-induced RAS signaling, so cancer cells with overexpression of EGFR are more susceptible to VV infection." (PMID 39430750, 2024). "EGFR inhibitors block signaling pathways involved in cancer cell proliferation and survival, as well as host-dependent processes that promote cancer growth." (PMID 39881923, 2024). "Targeting EGFR reduces cancer progression and cancer pain, presumably by interfering with pain mechanisms." (PMID 39000275, 2024). "To date, there are two main drug types for cancer-targeted therapy based on high EGFR expression: tyrosine kinase inhibitors (TKIs) and EGFR monoclonal antibodies." (PMID 38601214, 2024). "This present study also proved that the knockdown of EGFR or overexpression of miR-7a-5p abolished the accelerative role of AFAP1-AS1 overexpression in cancer progression and gemcitabine tolerance." (PMID 39574469, 2024). "The autophosphorylation of EGFR coordinates the simultaneous activation of PI3K/Akt signaling in cancer cells, facilitating the translocation of NF-κB to the nucleus." (PMID 39124760, 2024). "The target compounds were tested in vitro against various cancer cell lines and the EGFR and BRAFV600E enzymes." (PMID 39281035, 2024). "Firstly, we separated CTCs in clinical samples by size effect of microfluidic chips and found that EpCAM/EGFR/Her2 were widely presented as biomarkers in CTCs from peripheral blood of various cancer patients." (PMID 38720360, 2024). "EGFR monoclonal antibodies and small molecule tyrosine kinase inhibitors have achieved good therapeutic effects in clinical cancer treatment." (PMID 38817007, 2024). "Her2 and EGFR are known to be overexpressed on many cancer cells and both antibodies are successful clinical strategies." (PMID 37945970, 2024). "The dysregulation of MUC15 is observed in many cancers with links to EMT via EGFR inhibition, PI3K-Akt, and GSK3β/β-catenin signaling." (PMID 39483899, 2024).
cancer (continued). "Further dimerization alterations leading to cancer, such as heterodimerizations of EGFR with other RTKs, have been studied with MD, for which only the kinase domain is needed." (PMID 38612509, 2024). "Research mechanism of exosomal in cancer has achieved notable breakthrough, such as the clinical application of antivascular and EGFR‐TKIs resistance mechanism." (PMID 39247621, 2024). "It was inferred that saporin accumulates at high concentrations in the cytoplasm of cancer cells with high expression of EGFR, and specifically leads to cell death." (PMID 38790935, 2024). "In line with this, NUAK1 expression positively correlates with EGFR expression and Akt Ser-473 phosphorylation and malignant progression in several human cancers." (PMID 38201302, 2024). "Anti-EGFR antibodies, such as cetuximab, have proven to be effective in a variety of cancer types, including colorectal cancer, lung, and head and neck squamous cell carcinoma." (PMID 38315147, 2024). "This protein promotes cancer growth and treatment resistance by activating signaling cascades involving the epidermal growth factor receptor (EGFR), erythroblastic oncogene B2 (ErbB2), and mesenchymal-epithelial transition (MET)." (PMID 39408230, 2024). "EGFR is crucial for regulating and maintaining the biological characteristics of cancer, such as proliferation, invasion, and metastasis." (PMID 38706904, 2024). "While EGFR- and integrin αVβ3-targeting peptides hold significant promise for enhancing cancer diagnosis and treatment, extensive research and development are still required to address the existing challenges." (PMID 39126121, 2024). "EGFR is overexpressed in several malignant tumors, including lung, colon, liver, and breast cancers." (PMID 38699644, 2024). "The abnormal activation of EGFR in cancer cells can lead to uncontrolled cell growth, survival, and metastasis." (PMID 38605072, 2024). "A therapeutic target in many cancers, EGFR (also known as HER1 or ErbB1), is a receptor protein implicated in cell proliferation and invasiveness." (PMID 39742082, 2024). "So, blocking EGFR or intercellular adhesion molecule-1 (ICAM1) antibody neutralization in TAMs decreased cancer cell migration in mice." (PMID 39003350, 2024). "The top 10 cancer-related pathways included EGFR (ERBB1) downstream signaling, FGF signaling pathway, IGF1R signaling cascade, IRS-mediated signaling, and PI3K cascade." (PMID 38542291, 2024). "EGFR overexpression is correlated with poor clinical outcomes in solid tumors of human cancers, including breast, head, and neck cancers." (PMID 38534215, 2024). "It has been shown that combining a topoisomerase inhibitor with an EGFR inhibitor (e.g., gefitinib) is an effective treatment for breast and other cancer types." (PMID 38424554, 2024). "EGFR has been shown to be overexpressed in cancer, and EGFR antagonists have been used in cancer therapy, which is consistent with the results of this study." (PMID 38711062, 2024). "In line with this, EGFR is overexpressed in many types of cancer and EGFR antagonists are being evaluated in cancer therapy with promising results." (PMID 38526562, 2024). "In a previous study, PTEN deletion in H1650 cancer cells led to continuous Akt activation, providing a growth advantage even under EGFR inhibition." (PMID 38877005, 2024). "Evidence of peptide vaccines eliciting anti-tumor responses in GBM and NSCLC suggests the potential for the development of robust vaccines for other EGFR-mutant cancers, including LUAD, GBM, CRAD, and HNSCC." (PMID 38675381, 2024). "Consistent with previous reports highlighting the synergism of combined c-RAF/EGFR inhibition, DRx-170’s anti-cancer activity was enhanced when combined with the irreversible EGFR/ERBB family inhibitor afatinib." (PMID 38637546, 2024). "In this regard, it has been previously reported that cancer cells can indirectly activate neovascularization by triggering the EGFR signaling pathway and producing proangiogenic factors." (PMID 38158791, 2024).
cancer (continued). "For example, EGFR‐mutant non‐small cell lung cancer cells, as well as de‐differentiated and persistent cancer cells are vulnerable to ferroptosis due to their dependence on cystine and metabolic rewiring or the acquisition of a mesenchymal state." (PMID 39568772, 2024). "EGFRvIII, a mutated variant of the EGFR, represents the predominant form of this receptor in cancer, with approximately half of EGFR-amplified GBM cases expressing it." (PMID 38727262, 2024). "Separately, in cancers driven by EGFR, ERK provides suppressive phosphorylation of EGFR receptors, which is lost during MEK inhibition and leads to reactivation of ErbB3 and PI3K74." (PMID 39488530, 2024). "Palmitoylation is increasingly acknowledged as an important regulator of PM proteins, among which EGFR has been well recognized as a pivotal player in sustaining cancer cell stemness and a direct substrate protein for palmitoylation." (PMID 38263401, 2024). "With its simplicity and reliability, this biosensing system holds promise as a valuable tool for clinical EGFR detection, with implications for various cancers, including GBM." (PMID 38732975, 2024). "For example, immune checkpoint inhibitors (ICIs) can be very effective in advanced NSCLC (aNSCLC), but are only indicated in EGFR/ALK-negative cancers." (PMID 40027147, 2024). "We did not detect these target proteins in the current study, although EGFR is a very important biomarker in cancers." (PMID 38203840, 2024). "Recent studies have reported that the overexpression of DUBs such as Cezanne-1, USP22, and USP25 in cancer cells prevents EGFR degradation." (PMID 39048965, 2024). "In contrast, cases of invasive aspergillosis have been reported in patients with cancer who were treated with EGFR inhibitors including gefitinib, afatinib, erlotinib, and osimertinib (12, –, 15)." (PMID 39475281, 2024). "Epidermal growth factor receptor (Egfr) is important for normal cell growth, while overexpression of the receptor is a common route for cancer development." (PMID 38895364, 2024). "Targeted approaches in cancer management have been met with great success in various cancer types including BRAF in breast cancer or EGFR and KRAS in lung cancer." (PMID 39360054, 2024). "Our choice of TAA was the EGFR, a well-characterized tyrosine kinase receptor whose dysregulation promotes cancer cell proliferation, inhibits apoptosis, and promotes invasion." (PMID 38804302, 2024). "EGFR, IDH1, ARID1A, and CIC also displayed two associations each, while the remaining 68 hotspots corresponded to one gene associated with one specific cancer type." (PMID 38473427, 2024). "Recent studies on a range of drug-resistant cancers have consistently demonstrated that EGFR overexpression plays a pivotal role in driving both proliferation and angiogenesis." (PMID 39124760, 2024). "Our studies further reveal the many facets of IQGAP1’s role in mediating EGF signaling, hence indicating the potential of targeting IQGAP1 for novel anti-cancer therapies that can supplement the existing anti-EGFR chemotherapy." (PMID 39357822, 2024). "In vitro experiments revealed that compounds 8g, 8h, and 8l are effective cancer-fighting medicines that inhibit both EGFR and BRAFV600E." (PMID 39640522, 2024). "Desmoglein-1 also suppresses the EGF-induced EGFR-dependent formation of invadopodia, actin-based protrusions formed by cancer cells to facilitate invasion and metastasis." (PMID 39594667, 2024). "Prominent examples of targeted inhibitors used as first-line treatment in NSCLC are Osimertinib and Alectinib for advanced EGFR-mutant or ALK fusion-positive cancers, respectively." (PMID 38702301, 2024).